BCL2 (BCL2 apoptosis regulator)
Diseases named in the same sentence as BCL2 in open-access papers (continued):
Sharing a sentence is not in itself a finding about the gene and the disease.
cancer (continued). "Finally, from a different point of view, the synergistic effect demonstrated by PHNQs extract with Antimycin A in downregulating the anti-apoptotic Bcl-2 protein might be instrumental for a possible re-evaluation of Antimycin A in a combined therapy to overcome chemoresistance in cancer." (PMID 37760033, 2023). "Compound 12 had sub-micromolar anti-proliferative activity in cancer cell lines that express Bcl-2, as well as a sub-micromolar IC50 value in an ELISA experiment using the Bcl2-Bim peptide." (PMID 37259442, 2023). "Related studies had shown that when PCBP2 was knocked out, the expression of pro-apoptotic factor Bax was increasing and anti-apoptotic factor Bcl-2 was decreasing, and caspase-3 and PARP were activated to mediate apoptosis of cancer cells." (PMID 37814239, 2023). "Venetoclax, a selective Bcl-2 inhibitor, was approved by the Food and Drug Administration (FDA) several years ago for treatment of various cancers." (PMID 37899453, 2023). "Numerous studies have suggested that the abnormal activation of the PI3K/AKT signaling pathway contributes to the upregulation of Bcl-2 expression, leading to apoptosis-mediated MDR in various cancer therapies." (PMID 38186578, 2023). "To scrutinize, in various types of cancer cells, ICRN plays a decisive role through increasing cytochrome c secretion, Bax/Bcl2 ratio, poly (ADP-ribose) polymerase as well as caspase stimulations." (PMID 36662090, 2023). "Since safety and activity studies are underway in cancer clinics for MCL-1 and BCL-2 inhibitors, we expect that re-purposing them for TB treatment should translate more readily and rapidly to the clinic." (PMID 37864894, 2023). "Two of the top candidates, BCL-2 and SRSF2, are known to be non-synonymous drivers of cancer as cataloged in the Cancer Gene Census." (PMID 38062391, 2023). "MET targets the mTOR pathway in cancer cells, and WZB117 targets BCL2 to alter GLUT1 at the cancer site." (PMID 36850263, 2023). "Based on research in other hematological malignancies, the anti-cancer effects of decitabine can be enhanced by combination therapy with venetoclax (ABT-199), a BCL-2 inhibitor." (PMID 36765607, 2023). "This pathway controls genes such as BCL2, CCND1, and CCNB1, which are involved in cancer cell survival and proliferation." (PMID 36873868, 2023). "Specifically, the molecules involved in cancer-related pathways, including LAMB3, KEAP1, Bid, EGFR, Bcl-XL, Bcl-2, and PAX8, were all regulated by JorA." (PMID 37587470, 2023). "We found that a number of signaling networks and their components such as PI3K/Akt/mTOR, MMP‐2 and 9, Wnt/‐catenin, PARP, MAPK, NF‐κB, Caspase‐3/8/9, Bax, Bcl2, Smad4, Notch1, STAT3, Nrf2, and ROS signaling can be regulated in cancer cells by phytochemicals." (PMID 37132286, 2023). "The goal of this research is to characterize the packing interface between pro-survival BCL-2 proteins and the BH3 α-helix using the Knob-Socket method to inform the future development of cancer therapeutics." (PMID 36795726, 2023). "RNA-seq analysis of the effects of 24 h exposure of QN-302 on MIA PaCa-2 cells have previously shown that the mRNA levels in the prominent cancer pathway quadruplex-containing genes such as GLI1, MAPK11 and BCL-2 were downregulated by 1–2 fold." (PMID 36985425, 2023). "Based on the oncology array results, we demonstrated that melatonin exerts its anti-cancer effect by down-regulating the HIF-1α and NF-κB pathways and downstream pathways, including Bcl-2, leading to cell cycle arrest and apoptosis induction in the UBUC cells." (PMID 37086261, 2023). "After the co-culture with macrophages underwent lactate treatment, the level of E-cadherin decreased, while the levels of N-cadherin and Bcl-2 and the ratio of p-GSK/total GSK were all enhanced in the cancer cells." (PMID 36709284, 2023).
cancer (continued). "The major gene targets of four core herbs, MMP9, BCL2, STAT1, and STAT3, each as a subset of pathways in cancer, were confirmed to be involved in the MAPK pathway, the mTOR pathway, and cytokine–cytokine receptor interaction." (PMID 37631075, 2023). "In this study, our network pharmacology results showed that AKT1, AKT3, and BCL2 are hub targets, and KEGG pathway enrichment analysis revealed that PI3K-AKT signaling pathway is involved in the effect of Aloin A against cancer-related muscle atrophy." (PMID 38180061, 2023). "Overexpression of anti-apoptotic proteins of the BCL-2 family, such as BCL-2, BCL-xL and MCL-1, is frequently found in various cancers, including AML, thereby perturbing homeostasis of survival pathways and protecting cancer cells from death." (PMID 37726279, 2023). "Furthermore, by lowering the levels of Bcl-2 and up-regulating pro-apoptotic Bax expression in cancer cells, statins may enable the activation of the intrinsic pathway of apoptosis, thus facilitating the amplification of apoptosis signaling through the mitochondria." (PMID 37830584, 2023). "Understanding the balance between Bcl-2 and BAX expression is crucial for developing targeted cancer therapies that can restore normal apoptotic regulation and induce cancer cell death." (PMID 37185746, 2023). "BH3 mimetics to inhibit BCL-2, such as AbbVie’s venetoclax and Ascentage’s APG-2575 (lisaftoclax), are important new cancer therapeutics." (PMID 37685889, 2023). "This understanding has enabled the development of novel anti-cancer drugs, called BH3-mimetics, that can directly activate the apoptosis machinery by inhibiting pro-survival BCL-2 proteins." (PMID 36342579, 2023). "qRT-PCR of the following genes and main regulated processes: AKT and KI67 (cancer proliferation) as well as BAX and BCL2 (apoptosis) was performed." (PMID 37048115, 2023). "This “primed to death” status represents an Achilles’ heel in cancers that can be exploited by BH3-mimetic drugs (such as venetoclax), which antagonize anti-apoptotic BCL-2 proteins." (PMID 37684238, 2023). "BCL2 and KIT, i.e., oncogenes/proteins commonly overexpressed in tuft cell-like carcinomas, were expressed in one of the two triple-negative cases." (PMID 37179317, 2023). "The identification of the anti-apoptotic BCL-2 proteins as therapeutic targets has led to the development of BH3 mimetics, which have demonstrated efficacy in multiple cancer types in vitro as single agents or as sensitising agents." (PMID 35568716, 2022). "In esophageal carcinoma upregulation of miR-429, by targeting both Bcl-2 and SP1, promotes apoptosis in cancer cells." (PMID 36158660, 2022). "The cancer genes are composed of genes that code for HER2 (HER2 and GRB7), oestrogen genes (ER, PGR, BCL2, and SCUBE2), proliferation genes (MKI67, STK15, BIRC5, CCNB1, and MYBL2), and invasion genes (MMP11 and CTSL2) as well as GSTM1, CD68, and BAG1." (PMID 36042999, 2022). "MYC and BCL2 protein overexpression and RAS activation are oncogenic events that occur in many different cancers." (PMID 35563454, 2022). "Many of these genes were transcription factors and several of them were known cancer genes (e.g., APC, BCL2, ERBB2, HRAS, TGFBR2)." (PMID 35008420, 2022). "Silencing of this gene dramatically reduced resistance of CRC cells to fluorouracil and oxaliplatin and lowered the level of anti-apoptotic BCL2 protein in CRC and other types of cancer." (PMID 36010677, 2022).
cancer (continued). "Thanks to NF-κB overexpression, the NF-κB-induced expression of numerous antiapoptotic genes (such as those of Bcl-2, Bcl-xL, and c-IAP-2) has been observed in different types of cancers." (PMID 36276098, 2022). "CCDC26 participates in cancer cell growth and apoptosis by regulating the expression of PCNA and Bcl2." (PMID 36045445, 2022). "We also tested expression of Bcl2, which is an important anti-apoptotic factor previously correlated with CD44 expression in other human cancers." (PMID 35955749, 2022). "The EtOH extract, EtOAc soluble fraction, and GA extractives impaired the motility and invasion of cancer cells by prohibiting migration and proliferation by the downregulation of MMP2, MMP9, cleaved caspase-3, Bcl-2, and the upregulation of Bax." (PMID 36362345, 2022). "Calculating the cores’ quartile coefficients of dispersion (COD), a measure of the spread of the protein levels, we found that immune cells had a greater COD for BCL2 and BAK compared to cancer and stroma cells." (PMID 34754079, 2022). "In vitro experimental studies revealed that many phyto-colorants expressed anticancer activity through various mechanisms of targeting signaling mediators in cancer metabolism, including PI3K/Akt/mTOR, Bax/Bcl-2/caspases, and NF-kB/Nrf2." (PMID 36077338, 2022). "The level of mitochondrial anti-apoptotic protein Bcl-2 and Bcl-xL in both HCT-116 and MCF-7 cancer cell lines was determined." (PMID 35637622, 2022). "All experimental niosome groups had downregulatedexpression levelsof Bcl2, Drp1, MMP-2, and MMP-9 in both the 4T1 and SKBR3 cancer cellscompared to the control (p < 0.001)." (PMID 35129960, 2022). "Further mechanistic studies showed that compounds 1 and 11 induced apoptosis and inhibited the expression of anti-apoptotic Bcl-2 and Bcl-xL proteins in both HCT-116 and MCF-7 cancer cell lines." (PMID 35637622, 2022). "By neutralizing the antiapoptotic function of Bcl-2 proteins, BH3 mimetics are powerful compounds to induce apoptosis in cancer cells." (PMID 35013156, 2022). "Labile heme also causes the expression of oncogenes and cancer driver genes such as c-MYC, bcl-2, TGF-β, and Wnt by working on guanine quadruplex (G4) DNA structure as a heme-G4 DNA complex, resulting in a stimulation of cancer cell growth and proliferation." (PMID 36686754, 2022). "A recent study showed that berberine treatment suppresses cancer cell growth by regulating miR-22 and SP1, which are downstream targets of CCND1 and BCL2 in HCC." (PMID 35723348, 2022). "It is interesting to note that both API and miR-155 have common apoptotic targets in cancer cells such as caspase 3, caspase 9, FAS and Bcl2." (PMID 35892872, 2022). "As observed in other cancers, THZ1 synergized with the Bcl‐2 inhibitor venetoclax most likely in part by suppressing MCL‐1." (PMID 35253392, 2022). "Cancer cells are able to express a panel of anti-autophagy genes, such as Bcl-2, Akt, and PI3KC1, suggesting that autophagy can inhibit the transformation of normal cells into cancer cells." (PMID 35401195, 2022). "Overwhelming evidence has shown that antiapoptotic BCL-2 is activated while proapoptic BAK and BAX are inhibited in many cancers, affecting the resistance of cancer cells to drugs." (PMID 36411463, 2022).
cancer (continued). "It was found that MBZ inhibited S1P-induced cancer cell growth, and MBZ showed a growth inhibitory effect by regulating the JAK2/STAT3/Bcl-2 pathway." (PMID 36500220, 2022). "Various signaling pathways participate in the evodiamine-induced cancer cell apoptosis such as mTOR signaling, STAT3 signaling, and Bax/Bcl-2." (PMID 35899176, 2022). "The anti-apoptotic proteins (BCL-2, BCLXL, BCL-w, MCL-1, and BFL-1) are up-regulated in many cancers and hence have emerged as potential therapeutic targets." (PMID 35201512, 2022). "The cancer cells showed a decreased expression of various PI3k-AKT-mTOR pathways related to VEGF, COX-2, Bcl-2, NF-κB, and proteins post-treatment." (PMID 35774603, 2022). "The compound triggered G0/G1 cell cycle arrest by regulating the Bax/Bcl-2 imbalance and inactivating ERK1/2 and significantly restricted the proliferation of MCF-7 cells in other cancer cell lines." (PMID 35756648, 2022). "Compound 85 induced apoptosis by downregulating Bcl-2 and upregulating Bax protein levels in MDA-MB-231 cancer cells." (PMID 36297331, 2022). "Ole’s potential to impact PARPs, the Bax/Bcl2 ratio, the P38 MAPK pathway, HIF-1α, and the Akt and Jnk pathways disrupts cancer’s anti-apoptotic and angiogenic capabilities." (PMID 36013319, 2022). "Majority of the NRGs were deregulated in cancer tissues as compared to normal tissues which showed a uniform downregulated expression pattern except for NDRG2, BCL2, PRKN, TLR3, and STUB1." (PMID 36389725, 2022). "The EtOH extract, EtOAc soluble fraction, and gallic acid (GA) extractives impaired the motility and invasion of cancer cells by prohibiting migration and proliferation by the downregulation of MMP2, MMP9, Bax, cleaved caspase-3, and Bcl-2." (PMID 36362345, 2022). "Of these DEGs, 6 (EGFR, GATA3, DIABLO, CFLAR, RIPK3, and MAPK8) were repressed, while (ZBP1, PLK1, SPATA2, BCL2, ALK, FASLG, TNFRSF21, and LEF1) were upregulated in cancer cases." (PMID 35610275, 2022). "BCL-2 has been extensively studied in cancer, with the original BCL-2 inhibitor intended as a cancer treatment." (PMID 36569952, 2022). "In various cancers, aberrant STAT5 signaling increases the expression of target genes, such as cyclin D, Bcl-2, and MMP-2, eventually resulting in the promotion of cell proliferation, survival, and metastasis." (PMID 35563222, 2022). "The relative expression of Bax, Bcl-2, CCND1, and P21 genes that are involved in cancer was evaluated in this study." (PMID 35879795, 2022). "We found less literature on anthraquinone analogue binding mechanisms and interaction energy with caspase-3, apoptosis regulator Bcl-2, TNIK, and CDK2, important cancer-related protein targets." (PMID 36355520, 2022). "Bcl-2 and CCND1 genes, which promote cancer progression, have been reported to be important targets of miR-16." (PMID 35890348, 2022). "And these AML cells can fully utilize fatty acid oxidation to activate cancer-promoting signaling pathways such as AMPK, and up-regulate genes such as PPARγ, FABP4, CD36 and BCL2 genes to promote their own survival and proliferation." (PMID 36002858, 2022). "HepG2 and A549 cancer cells were treated with the IC50 of the CM derivative to evaluate the activity of topo I and topo II enzymes, and determine the levels of bax, and bcl2 proteins." (PMID 36432094, 2022). "G0S2 function traditionally relies on protein–protein interactions, such as BCL‐2,13 ATGL17, 67 or nucleolin, and G0S2‐mediated ATGL inhibition was shown to attenuate the growth of cancer cells." (PMID 36536477, 2022). "Studies have shown that CU or PTX can promote cancer cell apoptosis by inhibiting the phosphorylation of Akt in the PI3K/Akt pathway and then upregulating Bax and downregulating the expression of Bcl-2 protein." (PMID 35748365, 2022). "The same authors nicely demonstrated a relationship between BCL-2 pathway and RAS signaling in cancer stem cell providing the rational to design new strategy to treat resistant cancers." (PMID 36071980, 2022).
cancer (continued). "For example, G4s were shown to modulate the expression of key cancer genes, such as MYC, c-Kit, BCL2, and KRAS, with their disruption resulting in pronounced expression changes." (PMID 35573091, 2022). "Evodiamine exerted its anti-cancer activities through mitochondrial apoptosis induction, evident from increased levels of Bax, caspase–3 and PARP, while the expression of Bcl–2 and Survivin were decreased." (PMID 35956961, 2022). "VEGF, Ki67, Bax, Bcl-2, MTA1, and MMP2 expression in cancer tissues was consistent with those in cancer cells, as revealed by immunohistochemical staining." (PMID 34900992, 2021). "In our study, the expression of BCL2 and BCL2A1 in the differential hypermethylation pathway was down-regulated in A549 cancer cell line compared with normal lung epithelial cells." (PMID 34308964, 2021). "The downregulation of the PI3K/Akt pathway and NF-ĸB leads to changes in various related genes, NF-ĸB p65, GSK3B, XIAP, Bcl-2, VEGF, COX-2, PGE2, inducing apoptosis and inhibiting metastasis in cancer cells." (PMID 33540625, 2021). "On the other hand, as the ATV injection period is increased (τA = 0 → 1 → 4 → 10), the Bcl-2 level is increased and BAX activities are reduced, reducing the probability of apoptotic death of cancer cells through decreases in persistence of apoptosis." (PMID 34669701, 2021). "Because oxidative stress is one of the biological events in Res-treated cancer cells including GBM cells, the relevance of JNK and Bak, as well as of Bcl-2 in Res-treated C6 tumors was evaluated." (PMID 34638961, 2021). "In this regard, overexpression of anti-apoptotic BCL-2 members (e.g., BCL-2, BCL-XL, MCL-1) is quite frequent in newly diagnosed cancer as well as after developing resistance to therapies." (PMID 33799470, 2021). "ABT-737 binds BCL-2 and BCL-XL with a high affinity, and the drug has shown encouraging preclinical results with in vitro and in vivo models of cancers." (PMID 34830763, 2021). "The ΔCt values of 11 cancer-related genes (HER2, ER, PR, BCL2, CEGP1, Ki67, STK15, STMY3, CD68, GSTM1, and BAG1) were positively associated with HDL." (PMID 34456877, 2021). "In several kinds of hnRNPL overexpressing cancers, hnRNPL acts as an intron splicing factor that interacts with CA repeats in the 3′ untranslated region (UTR) of the Bcl-2 mRNA to prevent its degradation." (PMID 34333526, 2021). "HPV integration is most frequently detected in genic regions, most often cancer-related genes, such as oncogenes (e.g., TP63, MYC, ERBB2) or tumor suppressor genes (e.g., BCL2, FANCC, HDAC2, RAD51B, CSMD1) and to a lesser extent in miRNA regions." (PMID 34439243, 2021). "The suppressive effects of BCL-2 and CYP-1A1 are interlinked in cancer prognosis through migratory action and tumorigenesis." (PMID 35009072, 2021). "BCL2, CXCL8, and FGF1 promote cancer cell metastasis and invasion through EMT regulation in various cancers." (PMID 34199510, 2021). "In certain cancer types, we found a correlation between FGF-signalling, BCL-2 and MCL-1 expression and poorer patient prognosis." (PMID 34772930, 2021). "In this class of phytochemicals, puerarin act as a protective agent against ROS-induced apoptosis by decreasing Bax/Bcl-2 ratio and apoptosis, as well as preventing neuronal disorders such as Alzheimer’s disease and PC12 cancer cells." (PMID 34768743, 2021). "Many apoptosis-inducing agents induce cell death in cancer cells through the induction of the nuclear export of NR4A1, which can form a pro-apoptotic complex with bcl-2 to disrupt mitochondria and induce apoptosis." (PMID 34072371, 2021).